MYC (MYC proto-oncogene, bHLH transcription factor)
Diseases named in the same sentence as MYC in open-access papers (continued):
Sharing a sentence is not in itself a finding about the gene and the disease.
nasopharyngeal carcinoma (74 papers, 2008 to 2025). A carcinoma arising from the nasopharyngeal epithelium. "MYC can reprogram glucose metabolism in erythroleukemia cells and is involved in the occurrence and development of nasopharyngeal carcinoma." (PMID 40909263, 2025). "Studies have shown that EphA2 pS897 activates the AKT, STAT3, SOX-2, and c-MYC signaling pathways and plays a crucial role in nasopharyngeal carcinoma stem cell formation." (PMID 37063424, 2023). "Phosphorylation of EphA2 at S897 mediates the activation of the AKT, STAT3, SOX-2, and c-MYC signaling pathways, which is crucial to nasopharyngeal carcinoma stem cell formation." (PMID 37063424, 2023). "LINC01116 enhances the transcriptional activity of MYC to accelerate nasopharyngeal carcinoma progression." (PMID 33311496, 2020). "Cytoplasmic LINC01116 interacts with MYC mRNA to stimulate MYC protein and therefore enhance MYC transcriptional activity in nasopharyngeal carcinoma cells." (PMID 31703161, 2020). "Our results demonstrating that p38α promotes proliferation, by upregulating MYC mRNA levels are in line with the protumorigenic functions of p38 and with recent studies in breast, head and neck cancers and nasopharyngeal carcinoma." (PMID 29463565, 2018). "Additionally, in EBV-induced nasopharyngeal carcinoma, LMP1 facilitates increased interactions between MYC and the MYC target genes HK2 and IDH2, which encode enzymes in glycolysis and the TCA cycle, respectively." (PMID 34066504, 2021). "The contribution of LINC01116 to nasopharyngeal carcinoma progression is mediated by MYC." (PMID 31703161, 2020). "A previous report showed that β-catenin might be a regulator of stem cell markers and could affect the expression of SOX2, c-MYC and vimentin in nasopharyngeal carcinoma cells." (PMID 33089188, 2020). "Notably, c-MYC, a transcription factor that functions as an oncoprotein, is highly expressed in nasopharyngeal carcinoma cells and transcriptionally activates CHK1 and CHK2 in CSCs." (PMID 30800215, 2019). "SEs commonly achieve target gene activation through long-range chromatin looping, exemplified by MYC regulation in epithelial cancers via SE-driven chromatin architecture and SUCLG2-AS1 transcript-mediated SOX2 control in nasopharyngeal carcinoma." (PMID 40941410, 2025). "In nasopharyngeal carcinoma, reduced PPP2R2B expression activates PDK1/MYC pathways to induce BEZ235 resistance." (PMID 27888627, 2016). "Reduced PTEN and PPP2R2B expression correlated with activated AKT/mTOR and PDK1/MYC pathways, which can confer considerable BEZ235 resistance in nasopharyngeal carcinoma." (PMID 25762617, 2015). "Reduced PTEN and PPP2R2B expression correlated with activated AKT/mTOR and PDK1/MYC pathways and conferred considerable BEZ235 resistance in nasopharyngeal carcinoma." (PMID 25762617, 2015). "Wang and colleagues found that the overexpression of c-MYC activated DNA damage cell cycle checkpoints by upregulating the expression of the CHK1 and CHK2 checkpoint kinases in nasopharyngeal carcinomas, leading to the activation of DNA repair and ultimately resulting in radioresistance." (PMID 29396413, 2018). "A previous study indicated the ethyl acetate partition-enriched unknown compounds inhibit nasopharyngeal cancer CNE-1 cells by inducing Chk1-mediated G2/M arrest and suppressing MYC transcription." (PMID 29142311, 2017). "In this study, using an integrated analysis of acquired BEZ235-resistant nasopharyngeal carcinoma cells, we demonstrate that DNA methyltransferase is a key modulator and a common node upstream of the AKT/mTOR and PDK1/MYC pathways, which are activated in cancer cells with acquired BEZ235 resistance." (PMID 25762617, 2015). "We speculate that a PPP2R2B deficiency can induce MYC and P70 phosphorylation by impairing the binding of PP2A and MYC as well as PP2A and P70, thus modulating nasopharyngeal carcinoma resistance to BEZ235." (PMID 25762617, 2015).
nasopharyngeal carcinoma (continued). "miR-30-5p may represent a novel therapeutic target in NSCLC, colorectal cancer, and nasopharyngeal carcinoma since it can mitigate tumorigenesis through USP22 suppression, leading to Wnt/β‐catenin signaling target genes (Axin2 and MYC) and Sirt1/JAK/STAT3 signaling modulation." (PMID 35087589, 2022). "In nasopharyngeal carcinoma (NPC) cells, LINC01116 was shown to induce the translation of MYC and enhance the expression of MYC protein, which plays an essential role in proliferation." (PMID 34722518, 2021).
endometrial cancer (72 papers, 2008 to 2025). Primary or metastatic malignant neoplasm involving the endometrium (mucous membrane that lines the endometrial cavity). "Lastly, a more recent study using JQ1 demonstrated that JQ1-mediated reduction of c-MYC was associated with suppressed tumor growth in a xenograft mouse model as well as reduced proliferation and enhanced apoptosis of endometrial carcinoma cell lines in vitro." (PMID 38078012, 2023). "We found that single nucleotide polymorphisms (SNPs) in HNF1B, KLF, EIF2AK, CYP19A1, SOX4 and MYC were strongly associated with incident endometrial cancer." (PMID 32066633, 2020). "MYC gene amplification and high MYC expression are common events in some high-grade endometrial cancers and this is linked to worse survival characteristics." (PMID 29240775, 2017). "Upregulation of MYC via FGF signaling has been reported in endometrial cancer cells, and MYC amplifications have been associated with earlier disease recurrence in endometrial adenocarcinoma patients." (PMID 26170901, 2015). "We also find that progression from primary to metastatic endometrial cancer is associated with a further increase of MYC signaling and ATAD2 expression." (PMID 23393560, 2013). "Our data suggest that ATAD2 overexpression in human endometrial cancers is a consequence of 8q24 amplification and associated with MYC pathway activation." (PMID 23393560, 2013). "The loss of PR expression and functionality in endometrial cancer cells could stimulate MYC the expression of MYC." (PMID 31426393, 2019). "Metformin treatment also reduces endometrial cancer stem cells by significantly decreasing mitochondrial membrane potential, targeting MYC signaling and mitochondrial bioenergetics in stem-like cells of endometrial cancer origin." (PMID 38711526, 2024). "Qiu and colleagues (2016) used a small molecule bromodomain 4 (BRD4) inhibitor, JQ1, to target c-MYC in endometrial cancer cells using both cell culture and tumor tissue xenograft models." (PMID 38078012, 2023). "The following perspective article compares the similarities between endometriosis and endometrial cancer and presents preliminary data suggesting that targeting c-MYC with Omomyc reduces endometriotic cell proliferation and viability in vitro." (PMID 38078012, 2023). "One transcription factor whose overexpression induces EMT as well as immune evasion, angiogenesis, ECM remodeling, cell migration and invasion is c-MYC which is overexpressed in both endometriosis and endometrial cancer." (PMID 38078012, 2023). "In that study, JQ1 inhibited endometrial cancer growth in both models and this was associated with a reduction in c-MYC protein expression as well as reduced expression of c-MYC downstream targets." (PMID 38078012, 2023). "From a functional standpoint, upregulation of c-MYC in endometrial cancer cells in vitro was shown to induce EMT, drug resistance and invasion." (PMID 38078012, 2023). "Like other cancer types, c-MYC is highly expressed in endometrial tumors and immunohistochemical localization studies revealed a 78.3% positive rate of c-MYC in endometrial cancer tissues with amplified c-MYC in 25% of the cases." (PMID 38078012, 2023). "Similar to expression levels in endometrial carcinoma, c-MYC expression is also elevated in endometriotic lesion tissue as well as matched eutopic endometrium from women with endometriosis." (PMID 38078012, 2023). "A large body of evidence indicates multiple oncogenic roles of MYC in carcinogenesis, including the pathogenesis of endometrial cancer." (PMID 36140779, 2022).
endometrial cancer (continued). "One study exploring the role of androgen receptor (AC) in endometrial cancer suggested that KDM4B together with AR can activate the well-recognised oncogene, MYC, by removing H3K9me3 marks in endometrial cancer cells with high basal levels of AR." (PMID 33669182, 2021). "The associations between endometrial cancer and variants in or around HNF1B, CYP19A1, SOX4, MYC, KLF and EIF2AK found in earlier GWAS were then replicated in the latest and largest GWAS." (PMID 32066633, 2020). "In endometrial cancer, three differentially expressed ARGs (ERBB2, BAK1 and MYC), which are closely related to the occurrence of endometrial cancer, were increased." (PMID 33109128, 2020). "In endometrial cancer, patients with carcinosarcoma, serous adenocarcinoma and leiomyosarcoma showed many alterations of cancer driver genes, such as MYC and CCNE1." (PMID 30046040, 2018). "To examine the potential of SOX2, OCT4, NANOG, and MYC as prognostic markers in endometrial carcinoma, we correlated their expression with survival outcomes in patients." (PMID 30510261, 2018). "At this late time point, MYC was downregulated 1.8-fold on average in endometrial cancer patient samples and showed a 1.5-fold downregulation in head and neck cancer patients." (PMID 28443095, 2017). "Recent work has shown a role for the progesterone receptor in down-regulating MYC in endometrial cancers." (PMID 29240775, 2017). "Negative regulatory effects of PGR on MYC were reported for primary prostate tumors and in endometrial cancer." (PMID 28005952, 2016). "We took interest to this pathway because literature on MYC pathway dysregulation in endometrial cancer is limited." (PMID 26170901, 2015). "We performed an integrated analysis of copy-number and expression data to look for evidence that MYC is a target of 8q24 amplification in endometrial cancer." (PMID 23393560, 2013). "ATAD2 was co-amplified to the same level as MYC in nearly all tumors (as it was among our endometrial cancers)." (PMID 23393560, 2013). "Knockdown of either ATAD2 or MYC resulted in highly correlated decreases in viability across the seven cell endometrial cancer lines (R2 = 0.70, p = 0.020)." (PMID 23393560, 2013). "c-MYC is elevated in eutopic endometrium and endometriotic lesion tissue in patients with endometriosis and the disease shares many similar pathological characteristics with that of endometrial carcinoma." (PMID 38078012, 2023). "Thus, in addition to being a well-established target in multiple types of cancer, c-MYC also appears a plausible target for endometrial carcinoma." (PMID 38078012, 2023). "We showed significant abnormalities in the expression of cancer-promoting genes in tissues proximal to endometrial cancer, with higher expression of MYC, NR5A2, SNAI1, and TWIST1, in tumor-adjacent tissues than in tumors, which suggests field cancerization effect." (PMID 36140779, 2022). "Therefore, we first knocked down DDX5 in endometrial cancer cells by siRNA, and found that the protein expressions of both c-MYC and PAX8 were reduced." (PMID 35672291, 2022). "For validation, we asked whether GSOA could identify MYC pathway dysregulation in an independent endometrial cancer dataset." (PMID 26170901, 2015). "For example, endometrial cancer is characterized by intrachromosomal amplification of ESR1, KRAS, PIK3CA, ERBB2, TERC, MYC, CCNE1." (PMID 41415205, 2025).
endometrial cancer (continued). "In endometrial cancer, it binds to HMGA1 to promote c-MYC expression, accelerating the transcription of c-MYC-mediated glycolysis genes." (PMID 40379626, 2025). "The expression of MYC appeared necessary for SALL4-induced EMT, invasion, and resistance to antineoplastic drugs in endometrial cancer cells." (PMID 38539419, 2024). "METTL14 promotes tumorigenesis by upregulating expression of MYC and MYB in acute myelocytic leukaemia (AML) but acts as a tumor suppressor by inactivating AKT in endometrial cancer." (PMID 35047058, 2022). "As evidence, it has been shown that SALL4 is related to Car resistance in endometrial cancer by inducing epithelial-mesenchymal transition (EMT) and MYC expression, whereas reducing SALL4 expression enhances Car efficiency in endometrial cancer cells." (PMID 36362083, 2022). "Among these genes, CCR7, MYC and NOD2 have been reported in a large number of tumor studies, including endometrial cancer, while P2RX4, GNA15, and GPR132 genes have few molecular biological experiments to verify their role in endometrial cancer progress." (PMID 36207698, 2022). "Eight IRGs were incorporated to construct a nomogram for survival prediction in endometrial carcinoma patients, including CCR7, GNA15, GPR132, LTA, MYC, NOD2, P2RX4 and P2RY2." (PMID 36207698, 2022). "AR target genes such as XBP1, MYC, ZBTB16, and UHRF1 were previously reported to be induced by DHT treatment in AR-positive endometrial cancer MFE-296 cells." (PMID 29642629, 2018). "Recently, several groups reported that indirectly targeting MYC by the BET bromodomain inhibitor JQ1 exhibited anti-tumor activity in childhood sarcoma, thyroid tumor and endometrial cancer." (PMID 29156797, 2017). "However, the importance of MYC activation in endometrial cancer is essentially unknown." (PMID 23393560, 2013). "We find that ATAD2 amplification and expression is a prognostic marker in endometrial cancer and our findings suggest that development of specific ATAD2 inhibitors is a promising approach to treatment of endometrial and other MYC driven cancers." (PMID 23393560, 2013). "Endometrial CSCs isolated from endometrial cancer expressing stemness markers, including SOX2, OCT4, MYC, ABCG2, NES, and NANOG, have been demonstrated to show greater expansion potential and colony-forming capabilities, as well as to express self-renewal genes." (PMID 38539419, 2024). "We used cBioPortal and queried endometrial cancers present in the published TCGA cohort and found that those with copy number amplification or gain and elevated expression of MYC also had elevated ODC1 (p = 0.02) (data not shown)." (PMID 29240775, 2017). "Future studies should clarify the role of MYC and ODC in endometrial cancers." (PMID 29240775, 2017). "Although MYC is a likely target, the effects of this amplification in endometrial cancer have never been dissected." (PMID 23393560, 2013). "Our data indicate high ATAD2 expression is a marker of aggressive endometrial cancers, and suggest specific inhibitors of ATAD2 may have therapeutic utility in these and other MYC-dependent cancers." (PMID 23393560, 2013). "We found that both MYC and genes upregulated by MYC were overexpressed in endometrial cancers with 8q24 amplification relative to endometrial cancers without it (p = 0.047 and p = 0.0078, respectively)." (PMID 23393560, 2013). "Based upon the similarities between endometrial cancer and endometriosis and the fact that c-MYC appears to a common transcription factor with augmented expression and signaling in both endometrial cancer and endometriosis, it may also be a viable, non-hormonal treatment for endometriosis." (PMID 38078012, 2023). "Although univariate analysis showed that individual expression of SOX2, OCT4, and MYC correlated with survival, multivariate analysis revealed that SOX2 and MYC, but not OCT4, could function as independent prognostic factors in predicting survival of endometrial carcinoma." (PMID 30510261, 2018).
endometrial cancer (continued). "The association and the regulatory mechanisms of E2F family of transcription factors with UBE2C, MYC with UBE2C and the roles they play in the carcinogenesis of endometrial carcinoma have not been investigated, which offers new direction for the current research." (PMID 31942195, 2020).